MEG3 (maternally expressed 3)
Diseases named in the same sentence as MEG3 in open-access papers (continued):
Sharing a sentence is not in itself a finding about the gene and the disease.
breast cancer (continued). "•CXCR4 is the major downstream mediator negatively regulated by MEG3 that facilitates breast cancer cell migration." (PMID 40548301, 2025). "In this study, we first verified the decreased expression of MEG3 in breast cancer samples using bioinformatic analysis on TNM plot database as well as in breast cancer cell lines using RT-PCR." (PMID 40548301, 2025). "Consistent with previous reports, our results confirmed that MEG3 was a nuclear lncRNA with reduced expression in breast cancer cell lines." (PMID 40548301, 2025). "Our study together with these reports supported the model of MEG3/CTCF-CXCR4 axis in the cell migration of breast cancer development, in which CTCF serves as a transcription activator." (PMID 40548301, 2025). "In contrast, since the expression of MEG3 is lost or significantly reduced in breast cancer cells, CTCF is recruited to the promoter/enhancer region of CXCR4 to promote the transcription." (PMID 40548301, 2025). "MEG3, a genomically imprinted gene that was found to be significantly upregulated in circulating NK cells isolated from peripheral blood of breast cancer patients with fold change 46.85, P = 0.0138." (PMID 40781182, 2025). "Lastly, to further build up the correlation between the MEG3 expression level and breast cancer cell migration, we performed wound-healing assay on the MEG3-depleted MCF10A cells." (PMID 40548301, 2025). "The present study confirmed the downregulation of MEG3 in both tumour tissue and breast cancer cells, showing consistent effects on cell proliferation, migration, invasion, and apoptosis." (PMID 38240701, 2024). "MEG3 serves as a tumor suppressor in breast cancer by influencing on the expression of miR-182 and miR-29." (PMID 38535087, 2024). "The effects of lncRNA MEG3 on breast cancer malignant properties were evaluated by manipulating its expression in MCF-7 and BT-474 cells." (PMID 38240701, 2024). "For example, detecting the expression of lncRNAs like MEG3, CASC2, and others can help clinicians identify breast cancer at an early stage and improve diagnostic accuracy." (PMID 39479021, 2024). "The study showed reduced MEG3 expression in a Pan-cancer context and also demonstrated the reduced expression profile of the non-coding RNA molecule in high-invasive breast cancer cells compared to low-invasive cells." (PMID 40176927, 2024). "In dong’s study of breast cancer in vivo and in vitro, low expression of MEG3 sponge miR-141-3p affected cell proliferation performance and apoptosis, which was negatively correlated with high expression of miR-141-3p." (PMID 38347625, 2024). "An increasing number of studies have revealed that MEG3 is downregulated and represses cell proliferation, migration, and invasion, and induces apoptosis in breast cancer cells." (PMID 38240701, 2024). "The inhibitory effects of MEG3 on cancer progression have been reported in several other reports concerning breast cancer and other cancers such as squamous cell carcinoma of the head and neck, and lung, gastric, hepatocellular and colorectal carcinomas." (PMID 38277283, 2024). "Concerning our study, MEG3 was underexpressed (around minus 3.8-fold) in the tumors, which suggests its role as a further tumor suppressor lncRNA in breast cancer." (PMID 38277283, 2024). "Several studies have shown that lncRNA MEG3 is a critical prognostic factor in patients with breast cancer." (PMID 38240701, 2024). "MEG3 is down-regulated in breast cancer and is closely related to tumor size, lymph node metastasis, and TNM stage." (PMID 37901333, 2023). "The tumor suppressor LncRNA MEG3 is regulated by DNMT1’s hypermethylation in breast cancer, resulting in down-regulation of its expression." (PMID 37901333, 2023).
breast cancer (continued). "Conditioned medium aliquoted from breast cancer cells with MEG3 overexpression significantly reduced the capillary tube formation of endothelial cells." (PMID 36851033, 2023). "LncRNA MEG3 has been verified to be down-regulated and functioned as a tumor suppressor in multiple cancers, such as breast cancer, liver cancer, lung cancer and gastric cancer." (PMID 38309281, 2023). "Cisplatin induced anti-breast cancer effects at least partly by activating MEG3/NLRP3/caspase-1/GSDMD pathway." (PMID 36936274, 2022). "It has been reported that lncRNA MEG3 targets miR-421 to inhibit cell epithelial-mesenchymal transition (EMT) in breast cancer." (PMID 35109842, 2022). "First, we utilized western blot and qRT-PCR to assess DNMT1 and MEG3 levels in breast cancer cell lines (MDA-MB-231, SUM 149) and normal breast epithelial cell line (MCF10A)." (PMID 35109842, 2022). "For instance, overexpressed maternally expressed 3 (MEG3) was able to inhibit growth of breast cancer xenografts and promote cell apoptosis via regulating apoptosis related factors." (PMID 36685508, 2022). "In conclusion, silencing DNMT1 inhibited the malignant progression of breast cancer via up-regulating MEG3." (PMID 35109842, 2022). "It was showed that DNMT1 protein expression was significantly high in breast cancer cells, while MEG3 was significantly lowly expressed (p < 0.05)." (PMID 35109842, 2022). "Briefly, our results demonstrated that, DNMT1 induced methylation of MEG3 promoter, and played a key role in breast cancer growth throughmiR-494-3p/OTUD4 axis." (PMID 35109842, 2022). "Herein, we proved through RIP and dual luciferase experiment that MEG3 acted as a ceRNA of miR-494-3p in breast cancer." (PMID 35109842, 2022). "It is reported that DNMT1 can promote the malignant progression of breast cancer, while MEG3 can elicit a suppressive effect." (PMID 35109842, 2022). "An earlier example of this mechanism was observed during a thorough examination of the function of MEG3 in breast cancer." (PMID 35788171, 2022). "Then, rescue experiments were carried out to study modulation of MEG3/miR-494-3p axis in breast cancer cells." (PMID 35109842, 2022). "Bioinformatic analysis showed that estrogen receptor and progesterone receptor status in breast cancer were positively correlated with MEG3 expression." (PMID 35328609, 2022). "Knockdown of DNMT1 inhibited progression of breast cancer cells by enhance MEG3 expression through demethylation." (PMID 35109842, 2022). "Correlation between MEG3 and the prognosis and clinicopathology of breast cancer patients will be further discussed." (PMID 35109842, 2022). "The lncRNA MEG3 serves as a crucial molecule in breast cancer development, but the specific molecular mechanism needs to be further explored." (PMID 36033389, 2022). "In breast cancer cells, MEG3 has been shown to modulate the inhibition of E-Cad by sponging miR-421, resulting in the suppression of EMT." (PMID 35954272, 2022). "We also proved that MEG3 overexpression effectively inhibited development of breast cancer cells by targeting miR-494-3p/OTUD4 axis." (PMID 35109842, 2022). "Maternally expressed 3 (MEG3) is LncRNA and it was reported to be tumor suppressor in breast cancer." (PMID 34421993, 2021). "The expression of lncRNA MEG3 is reduced in breast cancer tissues and also in cell lines MCF7 and MDA-MB-231." (PMID 33414456, 2021). "Previous studies have shown that MEG3 was down-regulated in ER-positive breast cancer and is also closely related to the chemotherapy response of breast cancer and colorectal cancer." (PMID 34199840, 2021). "MEG3 rs7158663 G/A was genotyped and serum MEG3, miRNA-182, and miRNA-29 were measured in 180 breast cancer, 120 FA, and 150 controls by the qPCR." (PMID 34421993, 2021). "For example, MEG3 acts as a suppressor to inhibit cell epithelial-mesenchymal transition by sponging miR-421 and targeting E-cadherin in breast cancer." (PMID 32190687, 2020).
breast cancer (continued). "Chemoresistance posed a barrier to successful treatment of breast cancer (BC), and lncRNA MEG3 has been documented to implicate in BC development." (PMID 32618397, 2020). "For example, MEG3 is listed in the 32 downregulated core lncRNAs as being downregulated in various types of cancers including breast cancer." (PMID 32190687, 2020). "MEG3 expression was shown to be negatively correlated with survival of breast cancer patients, particularly with the luminal B subtype." (PMID 32612992, 2020). "Studies have demonstrated that some tumor-suppressive lncRNAs, e.g., LOC554202124 and MEG3 125,126, are downregulated by high level of CpG methylation at their promoters during breast cancer metastasis." (PMID 32929060, 2020). "For example, in breast cancer, up-regulating the expression of MEG3 had a potential to inhibit tumor growth by suppressing miR-21 via the PI3K/Akt signaling pathway." (PMID 32065781, 2020). "MEG3 expression is correlated with stromal markers in normal tissue and breast cancer tissue and negatively correlated with the survival of breast cancer patients in two different cohorts." (PMID 32612992, 2020). "Previous studies showed that MEG3 was downregulated in various types of cancers including breast cancer." (PMID 32190687, 2020). "In this paper we show that MEG3 expression negatively correlates with survival in breast cancer, particularly in grade three tumors and the luminal B subtype." (PMID 32612992, 2020). "The current result is consistent with results from previous studies, which showed that overexpression of MEG3 suppresses the proliferation of breast cancer cells." (PMID 32190687, 2020). "As a tumour suppressor, MEG3 has been found to suppress cancer development in various human cancer cells, including hepatocellular carcinoma, oesophageal cancer and breast cancer." (PMID 32519748, 2020). "We have shown that MEG3 negatively correlates with survival of luminal B breast cancer patients and patients with grade 3 breast cancer." (PMID 32612992, 2020). "On the other hand, CARMN, PRINS and MEG3 probably have an important role in pathogenesis of all subtypes of breast cancer." (PMID 33128008, 2020). "In breast cancer, MEG3 is known to be downregulated in cancer tissues and cells and MEG3 overexpression attenuates the tumorigenesis via PI3K/Akt pathway by sponging miR-2122." (PMID 31729423, 2019). "LncRNA MEG3 is lowly expressed in breast cancer cells, which is capable of inhibiting proliferation, migration and transformation of epithelial cells into stromal cells by targeting miR-412." (PMID 31123170, 2019). "MEG3 is downregulated and acts as a tumor suppressor in various cancer types including breast cancer, liver cancer, glioma cancer, colorectal cancer, cervical cancer, gastric cancer, lung cancer, ovarian cancer, and osteosarcoma." (PMID 31729423, 2019). "The major finding of the present study is that miR-506 inhibits migration and invasion of breast cancer cell lines through an undescribed pathway SP1/SP3/DNMT1/MEG3." (PMID 30386180, 2018). "Our data reveal a novel axis of miR-506/SP3/SP1/DNMT1/MEG3 in regulating migration and invasion of breast cancer cell lines, which provide rationales for developing effective therapies to treating metastatic breast cancers." (PMID 30386180, 2018). "Here, we show that miR-506 inhibits migration and invasion of breast cancer cell lines through the SP3/DNMT1/MEG3 axis." (PMID 30386180, 2018). "The lncRNA MEG3 has been shown to interact with chromatin and act as a repressive regulator in human breast cancer cells by RNA immunoprecipitation-coupled high-throughput sequencing." (PMID 28598385, 2017).
breast cancer (continued). "Given the functional interaction between MEG3 expression andTGF-β gene regulation in the breast cancer cell line BT-549,we extended our cell line analyses to the published clinical breast cancer datasets." (PMID 26205790, 2015). "One of the first lncRNAs to be associated with breast cancer survival was HOTAIR49 and as such we have shown that a second lncRNA (MEG3) is also associated with LN metastases further supporting the important role of lncRNAs in disease." (PMID 26537449, 2015). "MEG3 overexpression significantly inhibited migration in two breast cancer cell lines MCF7 (Luminal) and MDA-MB-231 (TNBC), but no noticeable differences were found between the two cell lines, indicating the effect of MEG3 on migration independent on the subtype of breast cancer." (PMID 40548301, 2025). "Furthermore, the low expression level of MEG3 has been correlated with poor prognosis in cervical cancer, meningioma, gastric cancer, colorectal cancer, and breast cancer." (PMID 40548301, 2025). "In addition, decreased MEG3 expression in breast cancer and colorectal cancer was strongly correlated with TNM stage and lymph node metastasis." (PMID 40548301, 2025). "Here we first verified the expression level of MEG3 in breast cancer using TNM plot database." (PMID 40548301, 2025). "Furthermore, lower expression of MEG3 was correlated to poor prognosis when the recurrence-free survival of breast cancer was assayed using Kaplan-Meier Plotter database (HR = 0.76 (0.69–0.85), p = 1.8e-07)." (PMID 40548301, 2025). "In addition, MEG3 has been widely studied in the context of ER stress in various cancers like breast cancer, cervical carcinoma, and colorectal carcinoma and can act as the potential therapeutic target for the prevention of tumor progression." (PMID 39448589, 2024). "Moreover, miR-330 mimics on the basis of lncRNA MEG3 overexpression ameliorated the tumor-suppressing effects of lncRNA MEG3 in breast cancer malignant properties by decreasing CNN1 expression." (PMID 38240701, 2024). "The data obtained in this study from the screening and validation experiments confirmed that PTENP1, GNG12-AS1, MAGI2-AS3 and MEG3 may have, or provide support for, potential tumor suppression roles in breast cancer." (PMID 38277283, 2024). "Furthermore, the expression of MEG3 was tightly correlated with the expression of Schlafen-5 (SLFN5), and overexpression of MEG3 ameliorated EMT in highly invasive breast cancer cells by modulating SLFN5 expression via MEG3/miR-146b-5p/SLFN5 axis." (PMID 40176927, 2024). "MEG3 was further shown to be a molecular sponge for miR-21 (suppressing the expression of this oncogenic miRNA); moreover, an in vivo experiment also proved that overexpressed MEG3 acted to inhibit tumor growth in breast cancer by suppressing miR-21." (PMID 38277283, 2024). "Similarly, recent findings revealed that the knockdown of DNMT1 inhibited the progression of breast cancer cells by enhancing the MEG3 expression through demethylation." (PMID 38277283, 2024). "Interestingly, MEG3 was seen to be highly expressed in the triple negative metastatic human Hs578T breast cancer cell line." (PMID 38277283, 2024). "The MEG3/miR-330/CNN1 axis provides a novel insight into the pathogenesis of breast cancer and may represent candidate therapeutic targets." (PMID 38240701, 2024). "Overall, the results supported tumor suppressor role of MEG3 in breast cancer." (PMID 38277283, 2024). "MEG3 was downregulated in breast cancer tissues and cell lines MCF-7 and MDA-MB-231." (PMID 36851033, 2023).
breast cancer (continued). "In an RNA-FISH study on breast cancer cells that showed considerable MEG3 expression (MEG3 is usually silenced in cancer tissues), the lncRNA formed many nuclear accumulation foci, suggesting that there could be interactions with multiple trans targets." (PMID 37686455, 2023). "LncRNA MEG3 regulates chondrogenic differentiation by inhibiting TRIB2, which is achieved by binding with EZH2 as well as LINC02273; it is associated with hnRNPL, which promotes metastasis of breast cancer by increasing AGR2 transcription." (PMID 38017487, 2023). "Moreover, the overexpression of MEG3 in breast cancer cells inhibited tumorigenesis and angiogenesis in the nude mice xenograft model." (PMID 36851033, 2023). "Similarly, the activating impact of DDP on pyroptosis was also eliminated by MEG3 knockdown, which indicates that MEG3 is crucial for pyroptosis in breast cancer." (PMID 36119049, 2022). "The diseases involving lncRNA MEG3 mainly include osteosarcoma, laryngeal cancer, prostate cancer, lung cancer, liver cancer, breast cancer, endometrial cancer, oral squamous cell carcinoma, gastric cancer, pancreatic cancer, colorectal cancer, and other malignant tumors." (PMID 36523500, 2022). "Furthermore, there was a positive correlation between MEG3 and heparan sulfate proteoglycan 2 expression in breast cancer tissues." (PMID 35328609, 2022). "Finally, a set of cellular experiments were done to assay the impact of MEG3/miR-494-3p axis on breast cancer cell viability, migration and proliferation." (PMID 35109842, 2022). "We also found that down-regulation of SNMT1 hampered progression of breast cancer cells, which could be reversed by MEG3 silencing." (PMID 35109842, 2022). "Intervention with MEG3 positively affected SLFN5 expression in breast cancer cells." (PMID 36033389, 2022). "Some studies validated our results; for example, MEG3 may be involved in regulating EMT process to inhibit breast cancer and pituitary development." (PMID 36033389, 2022). "Therefore, we further examined influence of the interaction of MEG3 with DNMT1 on the breast cancer cells." (PMID 35109842, 2022). "Despite this, MEG3 is less studied, especially in breast cancer." (PMID 35109842, 2022). "Upregulation of MEG3 suppressed the growth of breast cancer." (PMID 35109842, 2022). "In vitro functional experiments verified that upregulation of miR-494-3p could restore inhibitory effect of MEG3 overexpression on malignant behavior of breast cancer cells." (PMID 35109842, 2022). "MEG3 is a lncRNA that inhibits cell growth and metastasis of breast cancer cells." (PMID 33414456, 2021). "LncRNA Maternally expressed 3 (MEG3) has been identified as a tumor suppressor in breast cancer." (PMID 34421993, 2021). "In addition, MEG3 deactivated the AKT/mTOR signaling pathway by sponging miR-21, while miR-21 overexpression partially abolished the tumor suppressive function of MEG3 in breast cancer cells." (PMID 34527584, 2021). "Interestingly, even more genes are positively correlated to MEG3 expression in breast cancer as compared to normal breast tissue." (PMID 32612992, 2020). "In addition, MEG3 was highly expressed in stromal cells in breast tissue and its expression correlated with decreased survival in breast cancer." (PMID 32612992, 2020). "Meanwhile, MEG3 overexpression inhibits breast cancer cell proliferation and invasion, suggesting that MEG3 expression may also be regulated by aberrant CpG methylation in breast cancer metastasis." (PMID 32929060, 2020). "LncRNA MEG3 expressed abnormally in various cancers including breast cancer, but no studies reported the correlation between MEG3 SNPs and breast cancer susceptibility among Chinese women." (PMID 32669097, 2020). "According to previous studies MEG3 is down-regulated in breast cancer tissues." (PMID 33128008, 2020).